PATZ1 (POZ/BTB and AT hook containing zinc finger 1)
Description:
Transcriptional regulator that plays a role in many biological processes such as embryogenesis, senescence, T-cell development or neurogenesis. Part of the transcriptional network modulating regulatory T-cell development and controls the generation of the regulatory T-cell pool under homeostatic conditions. (Microbial infection) Plays a positive role in viral cDNA synthesis.
Synonyms: PATZ; RIAZ; ZBTB19; ZNF278; ZSG; MAZR; dJ400N23
Tractability: PROTAC: UniProt records ubiquitination sites on it; ubiquitination databases record sites on it; its protein half-life has been measured.
Gene: Protein-coding gene on chromosome 22 (31,325,804 to 31,346,605, reverse strand). Ensembl gene ENSG00000100105.
Subcellular location: Nucleus
Subcellular location (Human Protein Atlas): Nucleoplasm
Gene Ontology:
Molecular function: protein binding; ubiquitin protein ligase binding; DNA binding; DNA-binding transcription repressor activity, RNA polymerase II-specific; RNA polymerase II cis-regulatory region sequence-specific DNA binding; chromatin binding
Biological process: negative regulation of DNA-templated transcription; negative regulation of transcription by RNA polymerase II; regulation of cytokine production; regulation of DNA-templated transcription; regulation of immune system process; negative regulation of endothelial cell migration
Cellular component: nucleoplasm; nucleus
Genetic constraint (gnomAD): Loss-of-function variants: 9 observed, 47.43 expected, observed/expected ratio (o/e) 0.19, 90% interval 0.11 to 0.33. The upper end of that interval is the gene's LOEUF score, 0.33, which puts it in group 1 of 6, group 1 being the genes least tolerant of losing a copy. Missense variants: 632 observed, 972.74 expected, observed/expected ratio (o/e) 0.65, 90% interval 0.61 to 0.69. Synonymous variants: 426 observed, 403.47 expected, observed/expected ratio (o/e) 1.06, 90% interval 0.98 to 1.14.
Homologues: Orthologues: chimpanzee PATZ1 (99% identical), macaque PATZ1 (99% identical), dog PATZ1 (99% identical), mouse Patz1 (99% identical), rabbit PATZ1 (99% identical), rat Patz1 (99% identical), guinea pig PATZ1 (98% identical), pig PATZ1 (84% identical), tropical clawed frog patz1 (72% identical), zebrafish patz1 (56% identical). Paralogues in human: MAZ (22% identical), VEZF1 (21% identical), ZNF281 (17% identical), PRDM1 (16% identical), ZNF76 (15% identical), ZBTB16 (14% identical), ZNF143 (14% identical), MTF1 (14% identical), PRDM10 (13% identical), HIC1 (13% identical), ZNF148 (13% identical), ZNF384 (13% identical), and 24 more.
Diseases named in the same sentence as PATZ1 in open-access papers:
PATZ1 is named in the same sentence as 88 diseases in open-access papers, as found by Europe PMC text mining. Sharing a sentence is not in itself a finding about the gene and the disease. The quoted sentences say what the papers report.
sarcoma (22 papers, 2017 to 2025). A usually aggressive malignant neoplasm of the soft tissue or bone. "Patz1-knockout mice, either heterozygous or homozygous for a Patz1-null mutation, have an increased susceptibility to develop malignant tumors, including lymphomas, sarcomas, hepatocellular carcinomas, and lung adenocarcinomas." (PMID 29584698, 2018). "In sarcomas, CDKN2A alterations, reported in 71% of EWSR1::PATZ1 fusion cases in a series of 11 patients, are associated with aggressive phenotypes and poorer outcomes." (PMID 40575153, 2025). "The EWSR1::PATZ1 gene fusion was initially described in sarcomas, with only four published series documenting approximately 30 cases to date." (PMID 40575153, 2025). "Round cell sarcoma with EWSR1-non-ETS fusions includes two distinct entities, the EWSR1::NFATc2- and the EWSR1::PATZ1-fusion sarcomas." (PMID 40948502, 2025). "For example, EWSR1/FUS::NFATC2 sarcomas feature a marked male predilection, and EWSR1::PATZ1 sarcomas can arise in a broad age range, in contrast to Ewing sarcoma." (PMID 38339014, 2024). "Both homozygous and heterozygous Patz1-knockout mice developed a range of malignancies, including lymphomas, hepatocellular carcinomas, sarcomas, and, rarely, lung adenocarcinomas (1 of 36 Patz1+/− and 1 of 10 Patz1−/−)." (PMID 37046851, 2023). "EWSR1:PATZ1 fusions have also been reported in a subset of sarcomas occurring across a wide range of ages, with a predilection for occurrence in the chest wall, showing substantial heterogeneity in their morphology and immunoprofile." (PMID 34417833, 2021). "Chromosome 22-specific inversions that translocate the transcription factor EWSR1 with PATZ1 have been observed in various sarcomas." (PMID 32496219, 2020). "NFATC2 sarcoma may show significant epithelioid features, while PATZ1 sarcoma usually has a sclerotic background." (PMID 38427070, 2024). "The MN1-PATZ1 rearrangement, which has already been reported in the literature, may define a novel histological malignant pediatric brain tumor, which is closely related to PATZ1-sarcomas." (PMID 35204463, 2022). "NFATC2 sarcoma may exhibit epithelioid features, and PATZ1 sarcomas often display a sclerotic background." (PMID 33114111, 2020). "As with the sarcomas in which EWSR1:PATZ1 has been reported, the morphological variety, inconclusive immunoprofile and wide range of age at presentation are striking features that may account for the fact that these tumors have not been identified as a clear entity until now." (PMID 34417833, 2021). "Sarcomas with NFATC2 fusions tend to exhibit epithelioid features, while PATZ1 sarcomas are composed of largely undifferentiated round to ovoid neoplastic cells in a frequently sclerotic background." (PMID 36941503, 2023). "Genetically and clinically different round cell sarcomas were recently identified: round cell sarcoma with EWSR1-non ETS (NFATC2 and PATZ1 being the most common ones), CIC-rearranged sarcomas and sarcomas with BCOR genetic alteration." (PMID 34514574, 2021). "Among these, undifferentiated small round cell sarcomas (USRCSs) comprise multiple subcategories, including the recently described CIC-rearranged sarcomas, sarcomas with BCOR alterations, and non-ETS fused sarcomas (such as NFATC2 and PATZ1 sarcomas)." (PMID 38436779, 2024). "In comparison with data regarding PATZ1-fused sarcoma, the PATZ1-fused CNS tumors in this series were not enriched for homozygous deletions mapping to the CDKN2A/B locus (observed in only 2/59 cases, 3%)." (PMID 34417833, 2021). "These tumors comprise a heterogeneous category of old and new or emerging entities including morphologically defined sarcomas/neoplasms with EWSR1::CREB fusions and unclassified sarcomas with non-ETS EWSR1 fusions such as EWSR1::PATZ1 and EWSR1::NFATC2 fusions." (PMID 39031200, 2024). "The histology and immunoprofile of EWSR1:PATZ1-fused sarcoma has also been described as incredibly polyphenotypic, but MN1:PATZ1-fused sarcomas have not yet been described." (PMID 34417833, 2021).
neuroepithelial tumors (12 papers, 2021 to 2025). "They thus defined these PATZ1-fused neuroepithelial tumors as defined by y chromosome 22 chromothripsis." (PMID 39409964, 2024). "PATZ1 fusion neuroepithelial tumors are beginning to be recognized as a distinct molecular class of neoplasms that most often occur in children and young adults." (PMID 36816978, 2023). "Neuroepithelial tumors with PATZ1 fusions (NET-PATZ1) are a diverse group of mostly pediatric tumors harboring fusions between nearby chromosome 22q12 region genes, i.e., MN1-PATZ1 or EWSR1-PATZ1." (PMID 36604386, 2023). "Neuroepithelial tumors (NET) with PATZ1 fusions (NET-PATZ1) have been isolated by a distinct DNA methylation profile and are characterized by recurrent fusions of PATZ1 in association with EWSR1 or MN1 genes." (PMID 35115049, 2022). "In summary, PATZ1 fusions define a molecular class of histologically polyphenotypic neuroepithelial tumors, which show an intermediate prognosis under current treatment regimens." (PMID 34417833, 2021). "In conclusion, we describe here ‘neuroepithelial tumor with PATZ1 fusion’ (NET-PATZ1)—a novel, molecularly distinct CNS tumor type with strikingly variable histopathologic morphology and heterogeneous multiphasic differentiation patterns." (PMID 34417833, 2021). "The morphological heterogeneity, marker expression and pathognomonic fusions of PATZ1 with either MN1 or EWSR1 in this group lead us to suggest a name of ‘neuroepithelial tumor with PATZ1 fusion’ (NET-PATZ1)." (PMID 34417833, 2021). "Given their varied morphological appearance and defining fusions of PATZ1, as outlined further below, we provisionally suggest the term ‘neuroepithelial tumor with PATZ1 fusion’ to describe this molecular type." (PMID 34417833, 2021). "Neuroepithelial tumors (NEpT) harboring EWSR::PATZ1 fusions remain an enigma." (PMID 40575153, 2025). "This tumor group was provisionally called ‘neuroepithelial tumor with PATZ1 fusion’." (PMID 39409964, 2024). "The 4 emerging neuroepithelial tumors were diagnosed based on detection of the CIC, PATZ1, and PLAGL1 fusion genes." (PMID 40980447, 2025). "A novel DNA methylation class of tumor within the central nervous system, the "neuroepithelial tumor (NET), PATZ1 fusion-positive” has recently been identified in the literature, characterized by EWSR1- and MN1-PATZ1 fusions." (PMID 35115049, 2022).
glioma (10 papers, 2017 to 2025). A benign or malignant brain and spinal cord tumor that arises from glial cells (astrocytes, oligodendrocytes, ependymal cells). "In this study, we found that downregulation of PATZ1 expression in glioma patients was associated with poor prognosis." (PMID 35509848, 2022). "Here, we reported that the PATZ1 gene, which is highly expressed in adult GBMs and associated with the proneural subtype, is also highly expressed in a large subset of pediatric glial tumors." (PMID 31614588, 2019). "Overexpression of PATZ1 inhibits glioma cell proliferation and induces apoptosis by activating intrinsic apoptotic pathways." (PMID 35509848, 2022). "PATZ1 is known to localize in the stemness tumor compartment, where it can contribute to the maintenance of the glioma stem cells, similarly to what has been established in mouse embryonic stem cells." (PMID 31614588, 2019). "The PATZ1 gene has been recently shown to be expressed in adult gliomas, including glioblastomas, where it correlates with the proneural subtype and with a better prognosis." (PMID 31614588, 2019). "Similar to adult glial tumors, pediatric glial tumors showed a significant increase of PATZ1 expression compared to normal brain tissues (p = 1.33 × 10−3." (PMID 31614588, 2019). "This is consistent with a previous in vitro study showing that PATZ1 silencing in glioma cells enhanced their sensitivity to chemotherapeutic agents." (PMID 31614588, 2019). "Then, we assessed the correlations between PATZ1 expression levels and the clinicopathological features to explore the potential clinical significance of PATZ1 in pediatric gliomas." (PMID 31614588, 2019). "As far as pediatric gliomas are concerned, comprehensive genomic profiling has identified rearrangement of the PATZ1 gene with the Ewing Sarcoma-related gene, EWSR1 in a pHGG." (PMID 31614588, 2019). "Among high-grade gliomas, higher levels of PATZ1 have consistently been found to correlate with worse event-free survival." (PMID 31614588, 2019). "As for adult tumors, we show that PATZ1 is enriched in glial tumors compared to the normal brain, where it correlates positively and negatively with a proneural and mesenchymal signature, respectively." (PMID 31614588, 2019). "Consistently, PATZ1 expression, which has been found in the stem cell compartment of the tumor, is higher in glioma-initiating stem cells (GSCs) growing as spheres (likely proneural) than in GSCs growing as adherent cells (likely mesenchymal)." (PMID 31614588, 2019). "Here, we analyzed the expression of PATZ1 in pediatric gliomas, first at mRNA level in a public database, and then at protein level, by immunohistochemistry, in a cohort of 52 glial brain tumors from young patients aged from 6 months to 16 years." (PMID 31614588, 2019). "Further studies on the specific role of PATZ1 and its related genes in glioma stem cells will clarify this issue." (PMID 31614588, 2019). "Taken together protein and gene expression data, PATZ1 is overexpressed in gliomas compared to normal glia and appears as a specific biomarker of the proneural GBM subtype." (PMID 28938636, 2017). "Here we show that the transcription factor PATZ1 gene is upregulated in gliomas compared to normal brain and, among GBMs, is particularly enriched in the proneural subtype and co-localize with stemness markers." (PMID 28938636, 2017). "More recently, a comprehensive genomic profiling of pediatric gliomas identified a rearrangement of the PATZ1 gene (exons 1–5 of PATZ1 fused downstream to exons 1–9 of EWSR1) in a pediatric high-grade glioma." (PMID 29186807, 2017). "Accordingly, in GBM-derived glioma-initiating stem cells (GSCs) PATZ1 is overexpressed compared to differentiated tumor cells and its expression significantly correlates with the characteristic stem cell capacity to grow as neurospheres in vitro." (PMID 28938636, 2017).
glioma (continued). "On the other hand, it has been reported that PATZ1 knockdown by siRNA either inhibits the growth of colorectal carcinoma cells or increases the sensitivity of glioma cell lines to apoptotic stimuli, which indicates the tumor promoter function of PATZ1." (PMID 29137300, 2017). "PATZ1 overexpression was able to promote apoptosis of glioma cells." (PMID 35509848, 2022). "In this light, the selected genes, directly correlated with PATZ1 expression and belonging to the proneural signature, could be potential targetable molecules for new therapeutic approaches against pediatric gliomas." (PMID 31614588, 2019). "The purpose of our study was to analyze the expression of PATZ1 in childhood gliomas and correlate it with the clinicopathological features, with the final aim of opening up a novel diagnostic and potential therapeutic option for children with this challenging malignancy." (PMID 31614588, 2019). "Indeed, 6 out of 7 patients with metastases (86%) showed high expression of PATZ1 in the glioma sample." (PMID 31614588, 2019). "Consistent with the enrichment of PATZ1 in the proneural subtype, we showed in our local cohort of gliomas, that patients with low PATZ1 score (0/+) had a worse overall survival (OS) than patients with high PATZ1 score (++/+++) (HR = 2.525, 95% CI = 1.208-5.280, p = 0.0138)." (PMID 28938636, 2017). "Inhibition of the gene for the transcription factor PATZ1 (POZ/BTB and AT Inhibition of the transcription factor gene PATZ1 (POZ/BTB and AT hook containing zinc finger 1) by siRNA increased the sensitivity of the glioma cell line to apoptotic stimuli." (PMID 35846075, 2022). "Here we characterized the expression of PATZ1 in human gliomas showing it is overexpressed compared to normal brain and is significantly enriched in the proneural GBM subtype, where it behaves as a valuable prognostic marker." (PMID 28938636, 2017).
thyroid cancer (10 papers, 2015 to 2024). "The cytoplasmic delocalization of PATZ1, which is suggestive of a loss of function of the protein, is consistent with previous results in testicular germ cell tumors, thyroid carcinomas, and large B cell lymphomas." (PMID 37046851, 2023). "Since only few PATZ1 mutations have been so far reported in thyroid cancer (5 out of 50 PTCs, according to the International Cancer Genome Consortium-ICGC data portal), our idea is that PATZ1 is mostly epigenetically regulated during cancer progression." (PMID 30744101, 2019). "The purpose of this study was to investigate the role of PATZ1 in carcinogenesis of thyroid follicular epithelial cells and the mechanisms underlying the progression of thyroid cancer to more aggressive phenotype." (PMID 29137300, 2017). "Downregulation of PATZ1 expression in thyroid cancer cells has been associated with the activation of the Ras signaling, which leads to overexpression of miR-29b that, in turn, targets and downregulates PATZ1." (PMID 29186807, 2017). "However, the mechanisms underlying the role of PATZ1 in carcinogenesis of thyroid epithelial cells and progression of thyroid cancer remain unclear." (PMID 29137300, 2017). "Downregulation of PATZ1 in thyroid cancer appears to be a crucial event downstream of the Ras signaling." (PMID 30744101, 2019). "On the other hand, with the present work, we showed that PATZ1 enhances the stemness potential of rat thyroid cancer cells and tumor engraftment in nude mice, thus suggesting an oncogenic role." (PMID 30744101, 2019). "MAZR1, also known as PATZ1, has been shown to be downregulated and delocalized in thyroid cancer cell lines derived from papillary, follicular and anaplastic thyroid carcinomas." (PMID 31614935, 2019). "Another study has demonstrated the role of PATZ1 as a tumor suppressor in thyroid follicular epithelial cells and its involvement in the dedifferentiation of thyroid cancer." (PMID 31614935, 2019). "Accordingly, we previously showed a Ras-miR-29b axis involved in PATZ1 downregulation during thyroid cancer cell transformation, but it is likely that further mechanisms are involved." (PMID 30744101, 2019). "Recent results evidence a role for PATZ1 as tumor suppressor in thyroid cancer, involved in both carcinogenesis and cancer progression of thyroid follicular cells." (PMID 29584698, 2018). "The restoration of PATZ1 expression in thyroid cancer cells reverted their malignant phenotype by inducing mesenchymal-to-epithelial transition, thus validating a tumor suppressor role for PATZ1 and suggesting its involvement in thyroid cancer progression." (PMID 29584698, 2018). "Modification of PATZ1 expression altered the expression of uPA and MMPs in normal thyroid follicular epithelial cells and thyroid cancer cells in vitro." (PMID 29137300, 2017). "In conclusion, we demonstrated that PATZ1 plays an important role in both the process of carcinogenesis of thyroid follicular epithelial cells and in the progression and dedifferentiation of thyroid cancer." (PMID 29137300, 2017). "This study was designed to examine the involvement of PATZ1 in carcinogenesis and dedifferentiation of thyroid cancer." (PMID 29137300, 2017). "The frequency of positive nuclear PATZ1 expression decreased as the dedifferentiation of thyroid cancer progressed, and the frequency of nuclear PATZ1 expression in ATC was significantly decreased compared to that in NT/AG, DTC (i.e., PTC and FTC), or PDTC." (PMID 29137300, 2017). "Immunohistochemistry on clinical specimens indicated nuclear PATZ1 expression in all normal thyroid glands and adenomatous goiter, while nuclear PATZ1 expression decreased along with the dedifferentiation of thyroid cancer." (PMID 29137300, 2017).